NALCN (sodium leak channel, non-selective)
Diseases named in the same sentence as NALCN in open-access papers (continued):
Sharing a sentence is not in itself a finding about the gene and the disease.
glioma (2 papers, 2020 to 2021). A benign or malignant brain and spinal cord tumor that arises from glial cells (astrocytes, oligodendrocytes, ependymal cells). "Based on RNA sequencing (RNA-seq) results, we first identified a novel glioma-related circRNA, termed circNALCN (circBase ID: hsa_circ_0099761), which is derived from exons 2 to 7 of the sodium leak channel, non-selective (NALCN) gene." (PMID 34112159, 2021). "In addition, there is no report about CACNG2, JPH3, TUBB6 (tubulin β 6 class V), NRSN1, FAM19A2, NALCN, CDH18, GNAL on glioma." (PMID 32406502, 2020). "Most of them were reported in glioma, CACNG2 JPH3, TUBB6, NRSN1, FAM19A2, NALCN, GNAL have not been reported yet." (PMID 32406502, 2020). "CACNG2, JPH3, TUBB6, NRSN1, FAM19A2, NALCN, GNAL have not been reported in gliomas." (PMID 32406502, 2020). "In addition, CACNG2, JPH3, TUBB6, NRSN1, FAM19A2, NALCN, GNAL were not reported in glioma." (PMID 32406502, 2020).
head and neck cancer (2 papers, 2022 to 2023). A primary or metastatic malignant neoplasm affecting the head and neck. "Among 10,022 human cancers within The Cancer Genome Atlas, nonsynonymous mutations in NALCN were enriched in gastric, colorectal, lung, prostate and head and neck cancers 18,19." (PMID 36175792, 2022). "NALCN amplification is observed in all cases of endometrial cancer and head and neck cancer with genetic alteration." (PMID 37152978, 2023).
neuropathic pain (2 papers, 2023 to 2024). Chronic pain caused by damage to nerve fibers. "A recent study shows that the NALCN channel contributes to neuronal sensitization in neuropathic pain, and this result may lead experimental research to examine the regulatory mechanisms of NALCN by UNC79 and their associations with neuropathic pain in detail." (PMID 39526039, 2024).
prostate carcinoma (2 papers, 2023 to 2024). A carcinoma that arises from epithelial cells of the prostate gland. "Recent work uncovers a functional role for Na+ leak channel NALCN in prostate cancer, driving Ca2+‐dependent invasive cell remodeling and metastasis." (PMID 37635635, 2023). "Furthermore, in vivo experiments with prostate cancer have shown that the extent of PC-3-bone metastases depends on the bioavailability of NALCN in prostate cancer cells and that its expression in these cells increases with prostate cancer aggressiveness." (PMID 39766220, 2024). "Furthermore, the authors showed that the formation of invadopodial protein puncta occurs at sites of cytosolic Ca2+ wave initiation, which also coincide with high NALCN expression patterns in metastatic prostate cancer cells." (PMID 37635635, 2023). "NALCN downregulation further suppressed invadopodia formation and abolished prostate cancer cell invasion but not proliferation." (PMID 37635635, 2023).
respiratory depression (2 papers, 2023 to 2026). A decrease in ventilation secondary to impaired signals from the central nervous system. "Genetic deletion of NALCN in mice causes severe respiratory depression and postnatal lethality, and NALCN mutations in humans are associated with respiratory dysfunction." (PMID 41572053, 2026). "Notably, global inhibition of NALCN may cause abnormal functional outcomes, such as respiratory depression; therefore, the discovery of inhibitors targeting the peripheral nervous system, such as the DRG, may be more effective and safer." (PMID 38273833, 2023).
Akinesia (1 paper, 2021). Inability to initiate changes in activity or movement and to perform ordinary volitional movements rapidly and easily. "Few animal studies found that akinesia and freezing were the main phenotypes of NALCN-deficient strains; therefore, they put forward a hypothesis that the NALCN may be involved in movement disorders clinically characterized by akinesia and freezing gait in humans, such as PD." (PMID 35273550, 2021).
Anxiety (1 paper, 2023). Intense feelings of nervousness, tension, or panic often arise in response to interpersonal stresses. "Although there is no direct relationship between NALCN and anxiety, previous studies suggest that NALCN might be involved in the pathway between GABA receptors and anxiety and have been associated with neurodevelopmental changes that are associated with several anxiety-related risk factors." (PMID 38389806, 2023).
Apnea (1 paper, 2020). Lack of breathing with no movement of the respiratory muscles and no exchange of air in the lungs. "The apnea and neonatal lethality phenotypes are similar to those found in the NALCN KO12." (PMID 32620897, 2020). "UNC80 null, like those of NALCN and UNC79, have severe apnea and die shortly after birth." (PMID 32620897, 2020).
behavioral disorders (1 paper, 2020). "Thus, NALCN is an additional compelling candidate GDV-associated gene given its role in GI motility and ICCs and as well as its role in behavioral disorders such as hyperactivity." (PMID 33167491, 2020).
breast carcinoma (1 paper, 2024). "In contrast, treatment with 5’-aza-dC did not alter the expression levels of NALCN in the two breast cancer cell lines tested, BT20 and MDA-MB-468." (PMID 39766220, 2024).
Crohn disease (1 paper, 2024). A gastrointestinal disorder characterized by chronic inflammation involving all layers of the intestinal wall, noncaseating granulomas affecting the intestinal wall and regional lymph nodes, and transmural fibrosis. "Other novel CpG sites identified were previously associated with Crohn’s disease, inflammatory bowel disease, smoking, and age for NALCN (cg03185794) and ZNF792 (cg24678320)." (PMID 38571307, 2024).
diffuse large B-cell lymphoma (1 paper, 2023). "As a consequence, there was a strong correlation between NALCN expression and MMR genes in 32 cancers, aside from lymphoid neoplasm diffuse large B-cell lymphoma (DLBC), LUAD, OV, and UCEC." (PMID 37152978, 2023).
Encephalopathy (1 paper, 2019). Encephalopathy is a term that means brain disease, damage, or malfunction. "For example, gain-of-function mutations in the human NALCN gene cause encephalopathy and severe intellectual disability." (PMID 31601786, 2019).
endometriosis (1 paper, 2023). The growth of functional endometrial tissue in anatomic sites outside the uterine body. "Segregating variants in FGFR4, NALCN, and NAV2 were screened in 92 individuals with endometriosis and in 19 individuals with both endometriosis and an associated tumor." (PMID 37789421, 2023). "Here, we provide FGFR4, NALCN, and NAV2 as novel high-risk candidate genes for familial endometriosis." (PMID 37789421, 2023).
esophageal carcinoma (1 paper, 2023). A primary or metastatic malignant neoplasm involving the esophagus. "The results showed that the expression of NALCN was significantly associated with tumor stage in BLCA, COAD, esophageal carcinoma (ESCA), HNSC, KIRC, LUAD, READ, STAD, testicular germ cell tumors (TGCT), THCA, and UCEC." (PMID 37152978, 2023).
head and neck squamous cell carcinoma (1 paper, 2023). A squamous cell carcinoma that arises from any of the following anatomic sites: lip and oral cavity, nasal cavity, paranasal sinuses, pharynx, larynx, and salivary glands. "Using data from the TCGA database, results from 33 types of cancer in Cox regression illustrated that NALCN expression level was correlated with OS in adrenocortical carcinoma (ACC), BLCA, COAD, head and neck squamous cell carcinoma (HNSC), KIRP and brain lower grade glioma (LGG)." (PMID 37152978, 2023).
melanoma (1 paper, 2016). A malignant, usually aggressive tumor composed of atypical, neoplastic melanocytes. "Among genes mutated in at least two of those three melanomas, we identified TSC2 (tuberous sclerosis 2), CHD9 (chromodomain-helicase-DNA-binding protein 9) and NALCN (sodium leak channel, non-selective)." (PMID 27095580, 2016).
non-small cell lung carcinoma (1 paper, 2024). A group of at least three distinct histological types of lung cancer, including non-small cell squamous cell carcinoma, adenocarcinoma, and large cell carcinoma. "The mRNA expression levels of NALCN were quantified in non-small cell lung cancer (NSCLC) and adjacent non-cancerous tissues, and it was found to be underexpressed in 54.5% of tumor tissues, with significantly higher expression in recurrence-free patients (p = 0.009) than in patients who relapsed." (PMID 39766220, 2024).
sarcoma (1 paper, 2023). A usually aggressive malignant neoplasm of the soft tissue or bone. "For PFI, increased NALCN was a high-risk factor for BLCA, CESC, COAD, and sarcoma (SARC), and was a low-risk factor for LGG." (PMID 37152978, 2023).
skin cutaneous melanoma (1 paper, 2023). "Additionally, we can found NALCN was positively correlated with MHC-related genes in LIHC, LUSC, OV, PAAD, PRAD, TGCT, and THCA, while negatively correlated with MHC-related genes in ACC, CESC, GBM, KIRC, LGG, MESO, skin cutaneous melanoma (SKCM)." (PMID 37152978, 2023).
thyroid cancer (1 paper, 2023). "The expression of NALCN protein was higher in breast, cervical, colon, endometrial, liver, lung, ovarian, prostate, skin, and thyroid cancer than in normal tissues." (PMID 37152978, 2023).
cancer (15 papers, 2011 to 2025). A tumor composed of atypical neoplastic, often pleomorphic cells that invade other tissues. "More recently, Richard J. Gilbertson’s team also reported that NALCN regulates the transfer of epithelial cells to distant tissues, and loss of NALCN function promotes cancer metastasis." (PMID 40013144, 2025). "Secondly, although NALCN expression in human malignant tumor was associated with immunity, as well as clinical survival, how NALCN affected clinical survival through the immune route still unsure." (PMID 37152978, 2023). "Our work showed that NALCN is aberrantly expressed and is highly associated with prognosis for most cancer types." (PMID 37152978, 2023). "A dramatic increase in cancer metastasis with the deletion of NALCN in mice validates NALCN loss-of-function is a significant cancer metastasis driver." (PMID 37152978, 2023). "Our study aims to explore the potential diagnostic, prognostic and therapeutic value of NALCN in human cancers." (PMID 37152978, 2023). "Here, survival association analysis was conducted for each type of cancer using Cox regression analysis and KM survival curves, to examine the relationship between NALCN expression level and cancer prognosis, including OS, PFI, and DSS." (PMID 37152978, 2023). "In this work, NALCN RNA and protein were aberrantly expressed and NALCN closely associated with clinicopathological features in multiple cancers, such as stage, grade, molecular and immune subtypes." (PMID 37152978, 2023). "Nonsynonymous, cancer-associated mutations were clustered within the pore turret and voltage-sensing domains that regulate NALCN channel opening: 75% (n = 147/196) of these mutations were predicted to close the channel." (PMID 36175792, 2022). "Both de novo dominant and inherited recessive pathogenic variants of NALCN are described in severe pathological conditions in humans characterized by a wide range of symptoms, and NALCN is implicated in many other diseases, including psychiatric disorders and cancer." (PMID 40910942, 2025). "Moreover, NALCN was methylated in both cancer tissues and adjacent tissues, suggesting that loss of NALCN expression through methylation mechanisms is an early event in NSCLC tumorigenesis." (PMID 39766220, 2024). "NALCN loss-of-function mutations could help to reveal some enigmatic characteristics of human cancer." (PMID 37152978, 2023). "There is still much to learn about NALCN’s role in cancer and whether it can be used as a diagnostic, prognostic or therapeutic biomarker." (PMID 37152978, 2023). "While in gastrointestinal cancer, loss of NALCN enhances cancer metastasis." (PMID 37635635, 2023). "Upregulated NALCN expression was associated with poor or better prognosis in different cancers." (PMID 37152978, 2023). "Loss-of-function mutations in NALCN may also help explain various enigmatic features of human cancer." (PMID 36175792, 2022). "There is evidence that genes encoding the NALCN channelosome may contribute to the susceptibility for several diseases, including cardiac diseases, some cancers and psychiatric disorders." (PMID 33985508, 2021). "HOLE analysis, which usesa program for the analysis of the pore dimensions of the ion channel structural model, has shown that mutations that occur in advanced cancers and lead to loss of function of NALCN cause the greatest pore closure, suggesting that this channel may be a tumor suppressor." (PMID 39766220, 2024). "Consequently, these results suggested that NALCN may be a promising diagnostic biomarker for cancers." (PMID 37152978, 2023). "Mutations in NALCN could facilitate cancer progression in the parallel and linear models." (PMID 37152978, 2023). "NALCN has been identified as a tumor suppressor gene, and its role in human cancer progression has garnered significant attention." (PMID 40013144, 2025).
cancer (continued). "They discovered that the transport of epithelial cells to distant tissues is modulated by NALCN, thereby identifying NALCN as a critical regulator in cancer metastasis." (PMID 40013144, 2025). "Their findings indicate that NALCN expression exhibits tissue specific and is aberrantly regulated in multiple cancer types, indicating its potential as a crucial biomarker for cancer diagnosis." (PMID 40013144, 2025). "Deletion of NALCN has been shown to increase cancer metastasis and the number of CTCs in peripheral blood." (PMID 39766220, 2024). "Treatment with 5′-aza-dC induced the expression of NALCN only in the A549 cell line, suggesting that DNA methylation regulates its expression in certain cancers." (PMID 39766220, 2024). "A recent study described the proposed role of the sodium leak channel non-selective protein (NALCN) as a regulator of cancer cell shedding in different adenocarcinomas as well as normal epithelial cells lacking oncogenic alleles." (PMID 38520475, 2024). "Overall, these results suggest that DNA methylation regulatesthe NALCN expression in certain cancers, including NSCLC adenocarcinomas and meduloblastomas." (PMID 39766220, 2024). "In the present study, the role of NALCN in cancer was thoroughly examined and pan-cancer analysis was conducted through a comprehensive workflow." (PMID 37152978, 2023). "The results showed that NALCN expression significantly related to immune and stromal scores in most cancer types." (PMID 37152978, 2023). "From the perspective of the lack of pan-cancer study and further explore the role of NALCN in cancer, we analyzed NALCN across various cancer types based on large-scale RNA-sequencing data." (PMID 37152978, 2023). "The result implied that NALCN expression had a significant relation with TIICs for most types of cancer." (PMID 37152978, 2023). "It is suggesting that NALCN is involved in the progression of various cancers with prognostic value." (PMID 37152978, 2023). "In our study, we examined the association between NALCN expression and TMB, MSI, and well-known MMR genes in different types of cancer." (PMID 37152978, 2023). "In some cancers, upregulated expression of NALCN is detrimental to survival, while in others, it is beneficial." (PMID 37152978, 2023). "Top 3 cancers most significantly related to NALCN expression were ESAD, READ and STAD (stromal score); ESAD, LUSC and THYM (immune score); ESAD, READ and COAD (ESTIMATE score)." (PMID 37152978, 2023). "Forthcoming research exploring the functional coupling between NALCN‐mediated Na+ flow and Ca2+ fluctuations in other deadly human cancer entities will provide a better understanding of their therapeutic potential." (PMID 37635635, 2023). "In this study, we found that NALCN was significantly differentially expressed in 16 types of cancer." (PMID 37152978, 2023). "Most cancer types show strong correlations between NALCN expression and TMB, MSI, as well as MMR genes." (PMID 37152978, 2023). "We examined the relationship between NALCN mRNA expression level and patient’s clinicopathological features in pan-cancer using TISIDB tool." (PMID 37152978, 2023). "In the present work, we observed increased NALCN promoter methylation level and decreased NALCN mRNA expression appeared simultaneously across cancers." (PMID 37152978, 2023). "Recently, NALCN was identified as a regulatory protein in processes leading to cancer metastasis and in shedding of normal epithelial cells into circulation." (PMID 37789421, 2023). "Taken together, our study revealed the vital involvement of NALCN in cancer and developed a framework for further study of NALCN in cancer." (PMID 37152978, 2023).